RHOG (ras homolog family member G)
Diseases named in the same sentence as RHOG in open-access papers:
RHOG is named in the same sentence as 23 diseases in open-access papers, as found by Europe PMC text mining. Sharing a sentence is not in itself a finding about the gene and the disease. The quoted sentences say what the papers report.
glioblastoma (7 papers, 2012 to 2022). The most malignant astrocytic tumor (WHO grade IV). "We found that siRNA-mediated depletion of RhoG, using two independent oligos to minimize the risk of RNA off-target effects, strongly impairs invasion of two glioblastoma cell lines, SNB19 and U87, into brain tissue." (PMID 22966858, 2012). "Since EGFR is amplified and/or mutated in 45% of all glioblastoma tumors, we also examined whether RhoG mediates EGF-stimulated signaling in glioblastoma cells." (PMID 22966858, 2012). "Recently, research in our lab demonstrated that RhoG positively regulates cell adhesion, migration, and invasion through the activation of Rac in glioblastoma cells." (PMID 32089990, 2020). "RhoG was recently reported to be highly expressed in human glioblastoma and mediate glioblastoma cell invasion." (PMID 24844776, 2014). "We therefore also examined the role of RhoG in glioblastoma cell survival using a clonogenicity assay." (PMID 22966858, 2012). "We show that RhoG is critical for glioblastoma cell invasion, both in vitro and in ex vivo brain slices." (PMID 22966858, 2012). "Our finding that RhoG contributes to Rac1 activation downstream of EGFR in glioblastoma cells however, contrasts to published observations that EGF-stimulated Rac1 activation is independent of RhoG in HeLa cells." (PMID 22966858, 2012). "Here, we show that depletion of RhoG significantly inhibits both HGF- and EGF-stimulated Rac1 activation in glioblastoma cells, demonstrating that RhoG acts upstream of Rac1 in these cells." (PMID 22966858, 2012). "To examine the role of RhoG in glioblastoma invasion we first determined the effect of depleting RhoG on the invasion of glioblastoma cells into rodent brain slices, a well-established organotypic model." (PMID 22966858, 2012). "We found that siRNA-mediated depletion of RhoG strongly inhibits invasion of glioblastoma cells through brain slices ex vivo." (PMID 22966858, 2012). "Our functional analysis of RhoG in the context of glioblastoma revealed a critical role for RhoG in tumor cell invasion and survival." (PMID 22966858, 2012). "Our functional analysis of RhoG in the context of glioblastoma has revealed a critical role for RhoG in tumor cell invasion and survival." (PMID 22966858, 2012). "To further explore the mechanisms that mediate RhoG-regulated glioblastoma cell invasion, we examined the role of RhoG in the formation of two structures that have been implicated in Rac1-regulated cell migration and invasion: invadopodia and lamellipodia." (PMID 22966858, 2012). "In search of a mechanism for the contribution of RhoG to the malignant behavior of glioblastoma cells, we found that depletion of RhoG strongly inhibits activation of the Rac1 GTPase by both HGF and EGF." (PMID 22966858, 2012). "In this paper, we show that the small GTPase RhoG plays a critical role in glioblastoma cell invasion, both in in vitro and ex vivo settings." (PMID 22966858, 2012). "We observed that depletion of RhoG strongly inhibits glioblastoma cell colony formation, similar to the extent of depleting Rac1, indicating a significant role for RhoG in glioblastoma cell survival." (PMID 22966858, 2012). "miR-124-3p inhibited the viability of glioblastoma by targeting RhoG." (PMID 36009075, 2022). "Moreover, the TWEAK-Fn14 signaling discussed previously stimulates RhoG-dependent Rac1 activation and subsequently rebuts lamellipodium formation and enhances the invasive behavior of glioblastoma." (PMID 32089990, 2020). "Furthermore, RhoG-specific exchange factor SGEF mediates RhoG activation, which in turn activates Rac1 in glioblastoma cells." (PMID 32089990, 2020). "To start dissecting the signaling mechanisms that are mediated by RhoG in glioblastoma, we first examined whether RhoG is activated by HGF (hepatocyte growth factor, also known as scatter factor)." (PMID 22966858, 2012).
glioblastoma (continued). "Thus, our observations that both RhoG and Rac1 significantly inhibit glioblastoma cell colony formation, identify these GTPases as such signaling nodes." (PMID 22966858, 2012). "We therefore examined the role of RhoG in the invasive behavior of glioblastoma cells." (PMID 22966858, 2012). "We observed that depletion of RhoG has a small inhibitory effect on the proliferation of glioblastoma cells over a 5 day period in the presence of serum, but does not affect cell proliferation over the time period in which the brain slice invasion experiments are carried out (2 days)." (PMID 22966858, 2012). "In addition, depletion of RhoG has a marginal effect on glioblastoma cell proliferation, but significantly inhibits glioblastoma cell survival in colony formation assays." (PMID 22966858, 2012). "We also examined whether depletion of RhoG sensitizes glioblastoma cells to ionizing radiation, which is part of the current standard protocol for glioblastoma therapy." (PMID 22966858, 2012). "We also found that RhoG is activated by cMet and EGFR, two receptors that are deregulated in glioblastoma tumors, further underlining the relevance of RhoG-mediated signaling in the context of glioblastoma." (PMID 22966858, 2012). "In this paper, we focus on the role of RhoG in the invasive behavior of glioblastoma cells." (PMID 22966858, 2012). "However, immunohistochemical analysis revealed prominent cytoplasmic RhoG staining (with scores 2–3 out of 3) in glioblastoma cells in all 41 tumor samples tested." (PMID 22966858, 2012). "We therefore examined whether RhoG mediates HGF-induced Rac1 activation in glioblastoma cells." (PMID 22966858, 2012). "In addition, RhoG is important for glioblastoma cell survival, but less so for proliferation." (PMID 22966858, 2012). "Thus, RhoG contributes significantly to the malignant behavior of glioblastoma cells." (PMID 22966858, 2012). "Both RHOG and LSP1 are key regulators of cell proliferation and migration and play a critical role in regulating aggressive cancer cells, such as glioblastoma cells." (PMID 36057587, 2022). "It has been reported that RhoG, activated by EGF and hepatocyte growth factor (HGF), contributes to the formation of lamellipodia and invadopodia and promotes glioblastoma cell migration and invasion." (PMID 32089990, 2020). "SGEF is a RhoG-specific GEF, and also promotes cell migration and invasion in glioblastoma." (PMID 27437949, 2016). "Other Rho-family GTPases have not yet been examined, but RhoG merits consideration since it has been reported to stimulate membrane ruffling and macropinocyctosis and can activate Rac1 in response to EGF or HGF in glioblastoma cells." (PMID 25762935, 2015). "We also observed that RhoG is activated by both HGF and EGF, two factors that are thought to be clinically relevant drivers of glioblastoma invasive behavior, and that RhoG is overexpressed in human glioblastoma tumors versus non-neoplastic brain." (PMID 22966858, 2012). "We also demonstrate that RhoG mediates signaling that is stimulated by cMet and EGFR, two receptors that are deregulated in glioblastoma tumors and that RhoG is overexpressed in human glioblastoma tumor tissue versus non-neoplastic brain." (PMID 22966858, 2012).
breast carcinoma (6 papers, 2010 to 2022). "The modulation of RHOB and RHOG regulates the proliferation and differentiation of cancer cells, which influences the prognosis of breast cancer." (PMID 34991439, 2022). "In breast cancer, RHOG has been identified as a target gene of miR-124 in suppressing the metastasis of cancer cells." (PMID 34072894, 2021). "We have previously reported a correlation between nodal involvement and metastasis with raised levels of RhoC, RhoG and Rho6 in breast tumor tissue together with significantly higher levels of RhoC and RhoG in patients who died of breast cancer." (PMID 29147173, 2010).
glioma (4 papers, 2013 to 2022). A benign or malignant brain and spinal cord tumor that arises from glial cells (astrocytes, oligodendrocytes, ependymal cells). "RhoG can also activate Rac1 and Cdc42 in the regulation of neuronal process plasticity, thus it remains a possibility that deregulated neuronal signaling and development pathways may also utilize RhoG to promote glioma malignancy." (PMID 24109588, 2013). "Further studies have shown that ARHGEF16 activates RhoG and PI3K, contributing to apoptosis resistance in tumor cells, and interacts with CKAP5 to promote the proliferation and migration of glioma cells." (PMID 35680563, 2022).
cervical cancer (2 papers, 2016 to 2021). A primary or metastatic malignant neoplasm involving the cervix. "In cervical cancer, EPHA2 activated AKT in a RhoG-dependent manner to promote the survival of HeLa cells." (PMID 33834064, 2021). "In HPV16-positive cervical cancer cells, RhoG activity is upregulated and E6 contributes to this upregulation by forming a complex with DLG1 and a RhoG guanine exchange factor (SGEF)." (PMID 26797638, 2016).
lung carcinoma (2 papers, 2012 to 2019). "Different from E2F3 and TFAP2C, GRHL2 can suppress tumor metastasis by regulating of transcriptional activity of RhoG in lung cancer." (PMID 30967126, 2019).
astrocytoma (1 paper, 2012). "Available microarray expression data, such as NCBI dataset GSE4290, did not reveal any significant change of RhoG mRNA expression levels across non-neoplastic brain and different grades of astrocytoma (data not shown)." (PMID 22966858, 2012).
cervical tumour (1 paper, 2012). "To do this we first analysed the levels of RhoG activity in HPV-18 positive cervical tumour derived HeLa cells." (PMID 22383878, 2012). "We also show that a discrete pool of Dlg is maintained in complex with E6 and SGEF in HPV-18 positive cervical tumour-derived cells, which in turn contributes to maintaining high levels of RhoG activity and thus directly contributes to the invasive potential of these cells." (PMID 22383878, 2012). "In order to determine whether E6 could have any influence on the activity of the hDlg/SGEF/RhoG signaling network, we made use of HPV-18 containing HeLa cells that are derived from a cervical tumour." (PMID 22383878, 2012).
human papillomavirus infection (1 paper, 2021). "Previous work has demonstrated that the Scribble complex members DLG1 and/or SCRIB play key roles facilitating ARHGEF26 activity and RHOG activation during human papillomavirus infection, as well as in regulating epithelial junction formation, contractability, and lumen formation in 3D cysts." (PMID 34242364, 2021).
lung adenocarcinoma (1 paper, 2018). A carcinoma that arises from the lung and is characterized by the presence of malignant glandular epithelial cells. "Silencing of SGEF effectively suppressed the invasion and migration of human lung adenocarcinoma cells in vitro by inhibiting RhoG activity, and over-expression of SGEF could reverse this phenomena." (PMID 29454349, 2018).
proliferative vitreoretinopathy (1 paper, 2020). Vitreoretinal membrane shrinkage or contraction secondary to the proliferation of primarily retinal pigment epithelial cells and glial cells, particularly fibrous astrocytes, followed by membrane formation. "In conclusion, the miR-124/RHOG axis might be a potential therapeutic target in proliferative diseases affecting RPE cells, such as proliferative vitreoretinopathy." (PMID 32963317, 2020).
schizophrenia (1 paper, 2014). A major psychotic disorder characterized by abnormalities in the perception or expression of reality. "ARHG (also known as RHOG) family genes are associated with schizophrenia which encodes a member of the Rho family of small GTPases." (PMID 25522158, 2014).
thrombotic disorders (1 paper, 2013). "Interestingly, tail bleeding times were normal in RhoG−/− mice, suggesting that the functions of RhoG in platelets are particularly relevant to thrombotic disorders." (PMID 24106270, 2013).
thymoma (1 paper, 2022). A neoplasm arising from the epithelial cells of the thymus. "RhoG has been implicated in thymoma in type AB thymoma (cBioPortal) caused by a RhoG mutation at Ala151Ser." (PMID 35280994, 2022). "According to the cBioPortal and TCGA datasets (accessed December 2021), RhoG is frequently altered by amplification, deletion, or mutation, and aberrant RhoG gene expression has been observed in various malignancies, including thymoma." (PMID 35280994, 2022). "Although information about RhoG in T cell-related diseases is limited, mutant forms of RhoG, Ala151Ser and Glu171Lys have been observed in thymoma and hemophagocytic lymphohistiocytosis (HLH), respectively." (PMID 35280994, 2022). "Nonetheless, given the evidence of RhoG’s involvement in thymoma and lack of its function in the regulation of thymocyte development, RhoG Ala151Ser mutation may affect the activities of other small Rho GTPases, such as Rac1 and Cdc42, leading to impaired thymocytes development." (PMID 35280994, 2022).
Yersinia pseudotuberculosis infection (1 paper, 2012). "Other publications however indicate that upon Yersinia pseudotuberculosis infection YopT cleaves RhoA as well as Rac and Cdc42 from nascent phagosomes and affects RhoG." (PMID 22792400, 2012).
cancer (12 papers, 2016 to 2024). A tumor composed of atypical neoplastic, often pleomorphic cells that invade other tissues. "This approach is necessary because RhoG and its associated proteins represent prospective targets for attack particularly in the therapy of cancer and immune-mediated illnesses." (PMID 35280994, 2022). "Ephexin4 is overexpressed in some cancer types, and activation of RhoG promotes cancer cell invasion, migration, and cell proliferation." (PMID 39675713, 2024). "Most of the literature indicates that RhoG plays an active role in cancer progression by promoting cell migration, proliferation, and angiogenesis, and its absence is related to the reduction of cancer characteristics." (PMID 35280994, 2022). "This established RHOG as a potentially promising new target for anti-angiogenesis therapeutic applications in cancer." (PMID 30781697, 2019). "Collectively, our data confirmed the essential role of RHOG in angiogenesis, shedding light on a potential new therapeutic target for cancer malignancy and metastasis." (PMID 30781697, 2019). "Ephexin4 is a guanine nucleotide-exchange factor (GEF) for RhoG and is involved in various RhoG-related cellular processes such as phagocytosis of apoptotic cells and migration of cancer cells." (PMID 30445756, 2018). "Ephexin4, a guanine nucleotide-exchange factor for RhoG, promotes engulfment of apoptotic cells and cancer cell migration in a RhoG-dependent manner, which is synergistically augmented by Elmo1, an Ephexin4-interacting protein." (PMID 28667327, 2017). "ARHGEF26 activates the Rho family of RhoG and also regulates cancer cell migration." (PMID 34440281, 2021). "While the mechanism of activation of CDC42/RAC1 by RHOG, the MAPK by RAC1, as well as the intersection with the RHOA/ROCK1/2 pathways remain topics for future work, we believe this study sheds the light on RHOG as a potentially promising target for anti-angiogenesis in cancer therapeutics." (PMID 30781697, 2019). "Ephexin4 interacts with EphA2 and activates RhoG, which leads to cancer cell migration." (PMID 30445756, 2018). "In fact, abnormal RhoG activation leads to promotion of cancer cell migration and invasion." (PMID 27437949, 2016). "In this regard, DLG1 deregulation to the cytoplasmic region has been shown to be important for HPV-positive carcinoma cell, as cytoplasmic DLG1 pools bound to E6 favor the activation of the GTPase RhoG, which in turn facilitates the invasive potential of these cells." (PMID 32264889, 2020).
tumor (10 papers, 2010 to 2025). "Our data revealed the critical roles of miR-22 in inhibiting Rho, RAC1, RhoG, and RhoH GTPase cycles at the tumor margin or outside the tumors." (PMID 39953622, 2025). "In the model, ITGA3 and TNFSF10 were identified as risk factors, with high expression adversely affecting the prognosis of PC patients, while CDK11A and RHOG were protective factors, with high expression being favorable for tumor prognosis." (PMID 38956290, 2024). "Considering that RhoGDI3 has tissue-specific expression, and that the regulation of GTPases by RhoG and RhoB, is involved in invasion, migration and tumor suppression, we decided to address its possible role in the progression of PDAC." (PMID 27832197, 2016). "RhoG remains one of the less characterized Rho family members and its role in tumor cells is largely unexplored." (PMID 22966858, 2012). "Taken together, these studies demonstrate that the SGEF/hDlg/RhoG module can directly control a tumour cell's invasive potential." (PMID 22383878, 2012). "In the current study, we set out to determine the individual roles of Rac1, Rac3, and RhoG in tumor cell diapedesis." (PMID 21776386, 2011). "Here we find that RhoG partially contributes to CCL2-induced tumor cell diapedesis." (PMID 21776386, 2011). "However, depletion of Rac3 or RhoG increased tumor cell diapedesis." (PMID 21776386, 2011). "Moreover, we analyzed the target small GTPases, RhoG and RhoB, and we found a clear reduction of RhoB in pancreatic cancerous cell lines, but not in non-cancerous pancreatic cells, that correlates with the fact that RhoB protein deletion promoted tumor formation." (PMID 27832197, 2016). "This suggests a negative effect of Rac3 and possibly RhoG on tumor cell diapedesis." (PMID 21776386, 2011).
infection (4 papers, 2013 to 2021). The state of being infected such as from the introduction of a foreign agent such as serum, vaccine, antigenic substance or organism. "During infection, the cytosolic pool of activated RhoG and Rac1 is quickly depleted when infected with Y. pseudotuberculosis expressing YopE." (PMID 23390616, 2013). "During infection, YopT cleaves the prenyl modifications of membrane-bound RhoA, RhoG, Rac, and Cdc42." (PMID 23390616, 2013). "Infection with S. Typhi caused induction of IL-8, and levels were moderately lower in supernatants with ARHGEF26, but not with RHOG knockdown." (PMID 34242364, 2021). "Thus, YopH appears to play a major role in protecting Yptb from ROS production during tissue infection, in part through its ability to block SKAP2-controlled pathways, while YopE may play a more prominent role at the phagocytic cup in inactivating Rac1 and RhoG rather than in inactivating Rac2." (PMID 32392230, 2020).
RHOG also shares sentences with these, for which no sentence is quoted: breast tumor (1 paper); Hemophagocytic Lymphohistiocytosis (1); pancreatic cancer (1); retinal diseases (1); Salmonella Infections (1); Sepsis (1).